IL1B (interleukin 1 beta)
Diseases named in the same sentence as IL1B in open-access papers (continued):
Sharing a sentence is not in itself a finding about the gene and the disease.
Stroke (continued). "IL-1β is an inflammatory cytokine, and its role in human atherosclerotic disease was proven in the CANTOS trial, where anti-IL-1β monoclonal antibody infusions led to a significant reduction in nonfatal myocardial infarction, stroke, or cardiovascular death." (PMID 34197316, 2021). "By designing an IL-1β-neutralizing antibody, this group demonstrated that intravenous administration of the anti-IL-1β antibody was able to preserve BBB integrity following experimental stroke, although the exact mechanisms of this change were not identified." (PMID 29786644, 2018). "Among subjects with lacunar subtype and metabolic syndrome, PWV (after correction for age and gender) was more significantly and positively related to CRP, IL-1β, IL-6, TNF-α, vWF and PAI-1 compared to subjects without metabolic syndrome and the same subtype of stroke." (PMID 24571954, 2014). "In our experimental stroke studies, we could not detect increased cytokine production in the absence of microglial NKCC1 early (8 hours) after MCAo, while both IL-1α and IL-1β expression were markedly up-regulated in NKCC1 KO microglia 24 hours after reperfusion." (PMID 35085235, 2022). "Although no significant changes in pro-inflammatory cytokine (IL-1β, IL-6, TNF-α) and chemokine (MCP-1, MIP-2α) gene expression were observed at 6 h, 24 h and 72 h after the 50 min ischemic occlusion, IL-1β, IL-6 and MIP-2α expression tended to increase 6 h after stroke." (PMID 30842652, 2019). "Our study clearly revealed that KO mice exhibited extremely elevation of TNF-α, IL-1β, and IL-6, suggesting that the absence of IRAK-M can exacerbate the brain tissue injury of stroke through releasing larger amounts of proinflammatory cytokines in the acute phase of stroke." (PMID 30622459, 2018). "Up-regulated serum and brain pro-inflammatory cytokines elicited by TBI or stroke were attenuated by treatment with rhEPO, although EPO administration enhanced BDNF up-regulation elicited by cerebral ischemia, but did not prevent inflammatory gene up-regulation (e.g., IL-1β, IL-6, TNF-α)." (PMID 23675319, 2013).
gout (482 papers, 2005 to 2026). A condition characterized by painful swelling of the joints, which is caused by deposition of urate crystals. "MSU crystals activate the NLRP3 inflammasome, leading to interleukin-1β (IL-1β) release and neutrophil infiltration, causing gouty arthritis." (PMID 41019543, 2025). "MSU crystals are pro-inflammatory and can initiate, amplify, and sustain this response, with IL-1β playing a significant role in the inflammatory activity associated with crystal deposition in gout patients." (PMID 39861750, 2025). "We assessed this using a two-sample MR analysis in men and found evidence supporting a causal relationship between gout inflammation (two of the three positively association variants were in loci encoding genes central to IL-1β signaling) and prostate cancer." (PMID 40385401, 2025). "Bai Su Geng contains phenolics, coumarins, terpenoids, and alkaloids that mitigate gout‐associated inflammation and oxidative stress by suppressing IL‐1β/TNF‐α and scavenging free radicals." (PMID 40613560, 2025). "Given the central role that IL-1β plays in gout, this increase in cytokine production adds functional evidence to the genetic association of this variant with gout." (PMID 41155224, 2025). "Obesity predisposes to gout and amplifies inflammation through IL-1β and TNF-α signaling in adipose tissue, contributing to insulin resistance and cardiovascular risk." (PMID 41404505, 2025). "By investigating the changes in inflammatory mediators such as IL-1β and IL-6 during gout flares, scientists have found a significant association between their increase and joint pain and inflammatory responses in gout patients." (PMID 39980931, 2025). "Activation of the NLRP3 inflammasome has been implicated in the pathogenesis of gout, leading to the production of inflammatory cytokines such as IL-1β, IL-6, and TNF-α." (PMID 39907694, 2025). "These compounds inhibit the production of proinflammatory cytokines and enzymes, such as TNF-α, IL-1β, and cyclooxygenase-2, key contributors to the inflammatory response associated with gout." (PMID 39409183, 2024). "As a proinflammatory cytokine, IL-1β plays a crucial role in the inflammatory cascade that underlies gout flares." (PMID 39409183, 2024). "The ointment contains herbal components such as Aconitum carmichaelii and Notopterygium incisum, which inhibit key inflammatory mediators, including TNF-α, IL-1β, and IL-6, thereby reducing acute pain and swelling associated with gout flares." (PMID 39409183, 2024). "The formula contains bioactive compounds that inhibit inflammatory cytokines such as TNF-α, IL-1β, and IL-6 and enhance renal excretion of uric acid, providing both symptomatic relief and addressing the underlying causes of gout." (PMID 39409183, 2024). "MSU crystals, which cause gout, induce neutrophil infiltration and IL-1β secretion in an NLRP3 inflammasome-dependent manner when directly injected into the peritoneum." (PMID 39179640, 2024). "Typically, altered ATP levels can trigger the P2X7R-NLRP3 signaling cascade, leading to the secretion of IL-1β linked to gout attacks." (PMID 38094893, 2023). "Elevated PPARγ expression was also demonstrated in synovial cells of acute patients with gout and gene variation in PPARγ coactivator 1β was associated with IL-1β production in patients with gout." (PMID 37810213, 2023). "In order to further investigate the changes in inflammatory factors associated with gout, the expression levels of IL-1β, IL-6, and TNF-α were re-examined in serum." (PMID 37771709, 2023). "Our results underline the potential benefit of IL-1β inhibitors for treating gout flares in patients who fail or cannot tolerate standard therapy." (PMID 37491293, 2023). "When IL-1β is excessively produced, it can cause atherosclerosis, rheumatoid arthritis, gout, Parkinson's disease, Alzheimer's disease, tumors, and other diseases." (PMID 36193152, 2022).
gout (continued). "The NLRP3 inflammasome is a cytoplasmic protein complex that is implicated in IL-1β release and inflammation in various inflammatory diseases, including gout." (PMID 36234744, 2022). "NLRP3 and IL-1β have been identified as risk factors for gout, and it has been clinically confirmed that high levels of NLRP3, Caspase-1, IL-1β and IL-6 have been detected in serum and synovial fluid of patients." (PMID 36313318, 2022). "This is because IL-1β is a potent proinflammatory cytokine to cause neutrophil recruitment to the inflammatory loci, and plays a crucial role in the initiation step of gout triggered by MSU." (PMID 35098371, 2022). "During the inflammatory response of alcoholic liver injury and gouty arthritis, the uncontrolled IL-1β processed by NLRP3 causes the inflammatory response and induces the release of more proinflammatory cytokines and adhesion molecules." (PMID 36176434, 2022). "Pro-inflammatory cytokines have been implicated in initiation and amplification of the gout flare, such as IL-1β, IL-6, and TNF-α." (PMID 34586567, 2022). "The beneficial effects of anakinra have been demonstrated in the treatment of a wide range of disorders, including auto-inflammatory disorders, seizure, pericarditis, and gout, wherein the pathogenesis is associated with an excessive IL-1β expression." (PMID 36589291, 2022). "β-Carotene reduced inflammation in a mouse model of gouty arthritis caused by MSU crystals and reduced IL-1β release in human synovial cells from patients with gout, which suggest an antigout action." (PMID 36387275, 2022). "Dramatic changes in ATP levels can activate the P2X7R-NLRP3 signaling pathway and promote the IL-1β secretion associated with gout flares." (PMID 34925366, 2021). "In hyperuricemic patients, synergistic action between MSU and ATP is required to fully activate the NLRP3 inflammasome, which causes sufficient secretion of IL-1β, leading to the onset of gout flares." (PMID 34925366, 2021). "MSU crystals result in acute gout attacks characterized by IL-1β-driven acute inflammation, fever, and intense pain caused by neutrophil accumulation and activation in joints." (PMID 33535406, 2021). "The MSU stimulates abnormal IL-1β secretion to cause gout flares, which is achieved through recognition by Toll-like receptors (TLRs) or NOD-like receptors (NLRs) to activate the innate immune system." (PMID 34925366, 2021). "For instance, the deposition of MSU crystals promotes the local release of TNF-α and IL-1β, which causes persistent gout episodes." (PMID 34007291, 2021). "Collectively, our findings argue that the higher secreted IL-1β levels in gout PBMCs were associated with increased ROS levels in monocytes, potentially due to increased urate crystal uptake." (PMID 34992596, 2021). "The enhanced urate crystal phagocytosis by gout monocytes was associated with a significant increase in secreted IL-1β levels, at 2h, by gout PBMCs compared to normal PBMCs (p<0.05)." (PMID 34992596, 2021). "Recent studies have shown that, besides MSU, various purine metabolites, including adenosine triphosphate, adenosine diphosphate, and adenosine bind to different purine receptors for regulating IL-1β secretion implicated in the pathogenesis of gout flares." (PMID 34925366, 2021). "The TLR/MyD88/NF-κB receptor signaling pathway synergizes with the NALP3 inflammasome to activate IL-1β, which plays a key role in gout inflammation caused by MSU crystals." (PMID 34721647, 2021). "rs114362 in the IL-1B gene, interacting with a CARD8 variant (rs2043211), correlates with increased expression of IL-1β, IL-6, and gout risk." (PMID 33926105, 2021). "Rationale: The role of Monosodium Urate (MSU) crystals in gout pathophysiology is well described, as is the major impact of IL-1β in the inflammatory reaction that constitutes the hallmark of the disease." (PMID 32104502, 2020).
gout (continued). "Different studies have linked the deleterious effects of IL-1β with different pathological conditions, including type 1 diabetes, gout, Alzheimer’s disease and many auto-inflammatory disorders." (PMID 31991717, 2020). "A striking feature of these results is the lack of correlation between serum uric acid concentration and production of IL-1β in monocytes from gout patients, given that hyperuricaemia is the single greatest risk factor for gout." (PMID 30761138, 2019). "Mice deficient in NLRP3 fail to produce active IL-1β in the foot pads in response to MSU crystals in an acute gout mouse model." (PMID 31174271, 2019). "Interleukin-1β (IL-1β) is a pivotal proinflammatory cytokine that is strongly associated with the inflammation of gout." (PMID 29482609, 2018). "Recently, a seasonal, summer drop in the circulating protease inhibitor alpha-1 antitrypsin (and inversely higher stimulated IL-1β production) has been linked with increased summer flares of gout in a large European functional genomics consortium study." (PMID 28818081, 2017). "Gout is an inflammatory disease that is caused by the increased production of Interleukin-1β (IL-1β) stimulated by monosodium urate (MSU) crystals." (PMID 28797095, 2017). "Multiplicative interactions of the gout-associated IL1B risk genotype with that of CARD8 amplify the risk of gout." (PMID 28818081, 2017). "Gout is a polygenetic disease, and many studies of candidate genes have identified associations between inflammation-related genes such as IL-1β, IL-6, and IL-8 and susceptibility to gout." (PMID 26890073, 2016). "It is suggested by several studies that IL-1β, the pathological hallmark of the acute inflammatory attack, is a key regulatory pro-inflammatory cytokine in gout, which promotes a neutrophil influx into the synovium and joint fluid." (PMID 25897296, 2015). "Recent data support an important role for interleukin 1β (IL1β) in the inflammatory process associated with monosodium urate (MSU) crystal deposits in tissues of patients with gout." (PMID 19635719, 2009). "Prospective pharmacovigilance studies should evaluate whether concomitant administration of NLRP3 inhibitors (e.g., colchicine) or IL-1β-neutralizing biologics could mitigate FGF21-associated gout flare risk in predisposed individuals." (PMID 40388724, 2025). "The purpose of this study was to assess whether SU predicts CV risk in a trial of interleukin (IL)-1β inhibition with canakinumab, and whether IL-1β blockade, kidney function, or gout alter these associations." (PMID 39862678, 2025). "However, both IL-1β and IL-18 play an important role in the context of CV risk and therefore the activation of the inflammasome in gout opens up new scenarios worthy of discussion." (PMID 40710524, 2025). "Colchicine, an anti-inflammatory drug traditionally used to treat gout and pericarditis, has shown efficacy in reducing cardiovascular risk by inhibiting microtubule polymerization and suppressing cytokine release, including IL-1β and IL-6." (PMID 40072051, 2025). "Among these inflammatory cytokines, interleukin-1β (IL-1β) serves as a central driver of joint inflammation associated with gout by facilitating vasodilatation and promoting the recruitment of monocytes and the infiltration of neutrophils to areas where MSU crystals are deposited." (PMID 40635741, 2025). "These include geranylgeranyl transferase I beta subunit (PGGT1B), histone H3 protein (H3K4me1), IL-1β, interleukin-23 receptor (IL-23R), all of which may increase the risk of gout occurrence." (PMID 39432655, 2024). "The underlying mechanism of Prevotella in inducing gout inflammation might be by enhancing IL-1b production through activating NLRP3 inflammasome." (PMID 37344836, 2023). "Additionally, in vitro studies showed tart cherry inhibits IL-1β secretion, closely linked to gout flare initiation." (PMID 37679816, 2023).
gout (continued). "Upregulated tear uric acid and IL‐1β levels identified in the eyes of hyperuricemia patients imply IL‐1β‐mediated inflammation may be a plausible mechanism underlying hyperuricemia and gout‐associated ocular symptoms." (PMID 36988248, 2023). "Finally, this process leads to the release of active IL-1β from the cell, which causes an inflammatory effect and joint pain in gout patients." (PMID 36234744, 2022). "Activated IL-1β is secreted out of cells and then causes the recruitment and infiltration of inflammatory cells such as neutrophils and the release of more inflammatory mediators, promoting the occurrence and progression of the inflammatory response in gout." (PMID 36339582, 2022). "We explored whether gout-associated differential methylation might be implicated in regulation of IL-1β." (PMID 33493135, 2021). "Because IL-1β is a potent proinflammatory cytokine that causes inflammation at the initiation step of gout and neutrophil recruitment, we further asked whether DcR3 can inhibit the MSU crystal-induced inflammation in vivo." (PMID 33746978, 2021). "In addition to directly activating the NLRP3 inflammasome, MSU was found to stimulate the expression of P2X7 receptors and P2X4 receptors, secreting IL-1β and causing gout flares." (PMID 34925366, 2021). "For example, as one of the important proinflammatory cytokines strongly associated with the inflammation of gout, the IL-1β has been identified as the target of several miRNAs, though the regulatory roles of these miRNAs still need to be experimentally verified in vivo." (PMID 34359507, 2021). "In line with this information, an innovative multi-OMICs study, in which the cell-specific methylome was compared between gout patients and controls, revealed that many differentially methylated gene regulatory genomic sites were associated with IL-1β expression in monocytes." (PMID 34603340, 2021). "A number of researchers have confirmed that gout shares many pathogenetic features associated with other inflammatory disorders, i.e. a rapid increase in the secretion of some pro-inflammatory cytokines (IL-1β, IL-6 and TNF-α)." (PMID 32041665, 2020). "A human monoclonal antibody targeting IL-1β that was used in randomized control trials showed significant reduction in risk of developing first gout flares as well as the prevention of recurring gout flares." (PMID 32973552, 2020). "The fact that MSU increased ROS in human monocytes raised the possibility that this could be one mechanism by which crystallized uric acid could increase susceptibility to gout attacks by increasing the quantity of IL-1β secreted from monocytic cells." (PMID 30761138, 2019). "Therefore, IL-1β concentrations were analyzed in the supernatants of gout and hyperuricemia patients who carried all gout susceptibility genes." (PMID 28797095, 2017). "Both TNFα and IL-1β have recently been implicated in NETosis in rheumatoid arthritis and gout, suggesting they may contribute to NET formation also in AD." (PMID 28303140, 2017). "Therefore our aim was to test functional single nucleotide polymorphism (SNP) variants in the toll-like receptor (TLR)-inflammasome-IL-1β axis for association with gout." (PMID 26462562, 2015). "Another form of arthritis associated with the production of IL-1β is gout." (PMID 25975607, 2015). "Eleven functional variants were tested in eight genes involved in the MSU crystal-mediated activation of the NLRP3-inflammasome and production of mature IL-1β for association with gout in people of European and New Zealand (NZ) Polynesian (Māori and Pacific Island) ancestry." (PMID 26462562, 2015). "The major cytokine implicated in the pathogenic inflammation associated with gout is IL-1β." (PMID 24671093, 2014). "If the inflammation is hot (for example, during acute gout), the neutralization of IL-1β may cause pain reduction because TRPV1 is involved whereas this treatment will not reduce the mechanical hyperalgesia in chronic RA." (PMID 25606597, 2014).